ADAM23 (ADAM metallopeptidase domain 23)
Diseases named in the same sentence as ADAM23 in open-access papers (continued):
Sharing a sentence is not in itself a finding about the gene and the disease.
peripheral neuropathy (1 paper, 2021). A disorder affecting the peripheral nervous system. "In addition, previous data showed that CASPR2 and ADAM23 are active in the peripheral neuropathy by controlling the activity of potassium channels in SS." (PMID 33921415, 2021). "Based on the possible role of ADAM23 in the peripheral neuropathy, its involvement in IgM MGUS could be supported by some studies which have investigated a large cohort of MGUS patients and found that sensory/motor neuropathies were associated with IgM MGUS patients." (PMID 33921415, 2021).
ADAM23 also shares sentences with these, for which no sentence is quoted: autism (1 paper); autoimmune disease (1); brain cancer (1); COVID-19 (1); diabetes mellitus (1); Failure to thrive (1); focal epilepsy (1); HIV-1 infection (1); Hydrocephalus (1); ischemia (1); medulloblastoma (1); ovarian cancer (1); pancreatic cancer (1); Progressive encephalopathy (1); tonic-clonic seizures (1); Tremor (1).